S100B (S100 calcium binding protein B)
Diseases named in the same sentence as S100B in open-access papers (continued):
Sharing a sentence is not in itself a finding about the gene and the disease.
heart failure (3 papers, 2021 to 2024). Inability of the heart to pump blood at an adequate rate to meet tissue metabolic requirements. "Recently, S100B has also been implicated in cardiovascular diseases, including heart failure (HF)." (PMID 39201780, 2024). "At 1-year follow-up, the incidence of major cardiovascular events was higher in heart failure patients with increased S100B levels." (PMID 37217870, 2023). "As the expression of S100B in the heart tissue is induced by the remodeling processes, S100B may be a promising biomarker for establishing the diagnosis and prognosis in heart failure patients." (PMID 34821692, 2021).
hepatocellular carcinoma (3 papers, 2021 to 2023). A malignant tumor that arises from hepatocytes. "Recently, another study has elucidated the role of S100B in hepatocellular carcinoma (HCC)." (PMID 36766438, 2023). "S100B has been found to be dysregulated in many cancers including hepatocellular carcinoma (HCC)." (PMID 35368338, 2022).
Hydrocephalus (3 papers, 2017 to 2023). Hydrocephalus is an active distension of the ventricular system of the brain resulting from inadequate passage of CSF from its point of production within the cerebral ventricles to its point of absorption into the systemic circulation. "Hydrocephalus and elevated mean 8-day S100B levels predict poor clinical outcome one year after aSAH." (PMID 30011792, 2018). "In post aSAH hydrocephalus, high CSF and serum S100B levels for 10 days correlate with ventriculoperitoneal shunt placement." (PMID 30011792, 2018). "The highest lumbar GFAP and S100B concentrations were greater in moderate-to-severe than in mild hydrocephalus (P < .01 and P= .02, respectively)." (PMID 28605426, 2017). "Blood and cerebrospinal fluid (CSF) of children with TBM and hydrocephalus taken on admission and over 3 weeks were analyzed for the neuromarkers S100B, neuron-specific enolase (NSE), and glial fibrillary acidic protein (GFAP), in addition to multiple inflammatory markers." (PMID 28605426, 2017). "The association between severity of hydrocephalus and high GFAP and S100B concentrations suggests that these markers may be sensitive to transient injury due to the mechanical effect of dilating ventricles on the parenchyma, often accompanied by the opposing pressure from brain edema." (PMID 28605426, 2017). "CSF-DCX and CSF-GPC2 also correlated with hydrocephalus, the neuronal marker NSE, but not with the astrocyte marker S100B, acute infection or sex." (PMID 36800341, 2023).
Hyperammonemia (3 papers, 2014 to 2023). An increased concentration of ammonia in the blood. "In the present study, we proposed two circulating metabolites, S100B and 3-NT, that may have diagnostic utility in patients with congenital hyperammonemias." (PMID 36983411, 2023). "Thus, our results, for the first time, support S100B determination as a promising non-invasive diagnostic tool for inherited hyperammonemias." (PMID 36983411, 2023). "Additionally, hyperammonemia, low cholesterol levels, and the combination of serum S100B levels ≥ 35 pg/mL with MELD score ≥ 13 were factors for predicting 1- year mortality." (PMID 36766438, 2023). "Whether S100B increase may additionally exacerbate or compensate for CNS impairment in congenital hyperammonemias should be investigated." (PMID 36983411, 2023). "Overall, the linear correlation between ammonia and S100B but not standard oxidative stress-related markers offers a unique perspective for the future identification and monitoring of neurological deficits risk-linked with hyperammonemia episodes in patients with inherited hyperammonemias." (PMID 36983411, 2023).
Intestinal inflammation (3 papers, 2020 to 2021). "The clinical data and NSE and S100B protein levels of 81 children with seizure-associated mild gastroenteritis were collected." (PMID 33235129, 2020). "The purpose of this study was to determine the value of serum NSE and S100B protein levels for the differential diagnosis between CwG and FS associated with mild gastroenteritis." (PMID 33235129, 2020). "Therefore, this study retrospectively analyzed the serum NSE and S100B protein levels of infants with CwG and compared them with those of children with FS associated with mild gastroenteritis to investigate the difference in indicators of brain injury between the 2 diseases." (PMID 33235129, 2020). "Intestinal inflammation is associated with a parallel overexpression of TRPV1 and S100β along the gut–brain axis (colonic myenteric plexuses, dorsal root ganglion, and periaqueductal grey area)." (PMID 34829900, 2021). "This study summarized the clinical features of CwG and FS associated with mild gastroenteritis and retrospectively analyzed and compared the serum NSE and S100B protein levels of 46 patients with CwG and 35 patients with FS." (PMID 33235129, 2020). "This study aimed to evaluate the values of the serum NSE and S100B protein levels for the differential diagnosis between CwG and FS associated with mild gastroenteritis because relevant studies are lacking." (PMID 33235129, 2020).
intracranial hypertension (3 papers, 2018 to 2025). A finding characterized by increased cerebrospinal fluid pressure within the skull. "Nevertheless, patients with low eCPP presented higher levels of S-100β protein, suggesting that brain damage was directly related to hypoperfusion rather than intracranial hypertension." (PMID 39598064, 2024).
Intraventricular hemorrhage (3 papers, 2010 to 2025). Bleeding into the ventricles of the brain. "Second, S100B can be elevated in other conditions affecting the brain; however, the major confounder such as severe intraventricular hemorrhage was excluded." (PMID 40963746, 2025). "In the urine S100B concentrations at birth were significantly higher in preterm newborns developing intraventricular haemorrhage and/or brain damage." (PMID 20634930, 2010). "Increased blood concentrations of S100B were indeed detected in cases of chronic hypoxia and/or intraventricular hemorrhage (IVH) in preterm infants, in full-term infants suffering by perinatal asphyxia and adverse neurological outcomes." (PMID 20634930, 2010). "S100B was also measured in the blood of women whose pregnancies are complicated by intrauterine growth retard and whose newborns develop intraventricular haemorrhage." (PMID 20634930, 2010).
lymph node metastasis (3 papers, 2011 to 2022). "On the basis of this classification system we evaluated associations between MHA-3 or S100b and the presence of clinicopathological parameters, including pathological type, clinical stage and lymph node metastasis." (PMID 27853253, 2016). "Patients with lymph node metastases had increased S100B in 50.0% of cases compared to 57.1% of patients with distant visceral metastases." (PMID 21810220, 2011).
malaria (3 papers, 2021 to 2024). Malaria is a serious and sometimes fatal disease caused by a parasite that commonly infects a certain type of mosquito which feeds on humans. "In severe malaria, high levels of S100B in the CSF were associated with seizures in both Kenyan children and Vietnamese adults." (PMID 34905777, 2022). "Tau proteins were significantly elevated in children with cerebral malaria vs. malaria with prostration or malaria with seizures but normal consciousness, whereas S100B was associated with an increased risk of repeated seizures." (PMID 33115334, 2021). "Our group reported increased plasma levels of S100B in Indian patients with falciparum severe malaria compared to uncomplicated cases." (PMID 39658124, 2024). "Circulating levels of S100B, Tau, UCH-L1, BDNF, and NCAM-1 have been documented in previous malaria studies." (PMID 39658124, 2024).
myasthenia gravis (3 papers, 2019 to 2024). Myasthenia gravis (MG) is a rare, clinically heterogeneous, autoimmune disorder of the neuromuscular junction characterized by fatigable weakness of voluntary muscles. "For instance, increased levels of S-100B (one RAGE ligand) and RAGE are observed in experimental animal models of myasthenia gravis; and overexpression of HMGB1, CML(both RAGE ligands), and RAGE was found in the muscle fibers of polymyositis and dermatomyositis patients." (PMID 34620111, 2021).
non-small cell lung carcinoma (3 papers, 2018 to 2025). A group of at least three distinct histological types of lung cancer, including non-small cell squamous cell carcinoma, adenocarcinoma, and large cell carcinoma. "Research suggested that downregulation of S100B expression in non-small cell lung cancer (NSCLC) could significantly inhibit cell cycle progression, reduce colony formation, cell migration, and invasion activities, leading to decreased cell proliferation." (PMID 39314848, 2024).
oligodendroglioma (3 papers, 2008 to 2021). A well-differentiated (WHO grade II), diffusely infiltrating neuroglial tumor, typically located in the cerebral hemispheres. "MiRNA-124 is down-regulated in human oligodendrogliomas, and both miR-124 and miR-137 are down-regulated over 10-fold in S100β-v-erbB tumor stem cells relative to mNSCs." (PMID 18577219, 2008). "We first assessed differentiation of mOSCs derived from S100β-v-erbB transgenic mouse oligodendrogliomas." (PMID 18577219, 2008). "Furthermore, over-expression of the oncogenic form of EGFR (EGFRvIII) under the promoter S100b, a non-stem cell marker, induced gliomas recapitulating the pathological features of human oligodendroglioma." (PMID 29515370, 2018).
post-concussion syndrome (3 papers, 2017 to 2023). The organic and psychogenic disturbances observed after closed head injuries (HEAD INJURIES, CLOSED). "High levels of S100B are related to injury severity and predict the occurrence of post-concussion syndrome after mild TBI, poor clinical outcomes, and increased mortality." (PMID 37048647, 2023).
renal dysfunction (3 papers, 2013 to 2024). "Regarding renal dysfunction, our findings confirm a univariate association between S100B and eGFR, which was also described by others." (PMID 39201780, 2024). "Therefore, to establish the relationship between S100B levels and renal dysfunction in cirrhotic patients, further study using other renal biomarkers, such as cystatin C, is necessary." (PMID 36766438, 2023).
sarcoma (3 papers, 2016 to 2025). A usually aggressive malignant neoplasm of the soft tissue or bone. "We also found that EWS/ATF1-induced sarcoma cell lines express several Schwann cell marker genes such as P75NTR, S100b, Mbp, Plp1, and Pmp22 in vitro." (PMID 31488818, 2019).
tauopathies (3 papers, 2020 to 2023). "Together, our findings establish tau as a client of the S100B chaperone, providing evidence for neuro-protective functions of this inflammatory mediator across different tauopathies." (PMID 34725360, 2021). "Altogether, this study presents a mechanism with implications in AD and other tauopathies, implicating S100B as an extracellular holdase-type chaperone that mitigates tau aggregation and seeding." (PMID 34725360, 2021).
uveal melanoma (3 papers, 2021 to 2025). A melanoma derived from melanocytes of the uveal tract. "S100B serum concentration was also significantly higher in uveal melanoma patients with metastases compared to uveal melanoma patients without, and may potentially be a future biomarker for metastatic uveal melanoma." (PMID 35269741, 2022). "The expanded choroid, ciliary body, and iris were positive for S100b and negative for RPE65, consistent with the development of uveal melanoma." (PMID 39804140, 2025).
acute liver failure (2 papers, 2023). Rapid deterioration of liver function causing encephalopathy and coagulopathy. "Previously, it was demonstrated that serum S100B and IL-6 levels were associated with HE in pediatric patients suffering from acute liver failure, indicating that measuring these markers may be of benefit to the assessment of neurological injury, impacting clinical decisions." (PMID 36983411, 2023). "Taken together, obvious astrocyte swelling and damage developed in acute liver failure may release S100B protein; thus, elevated serum S100B may be a marker suggesting severe HE." (PMID 36766438, 2023).
AIDS dementia complex (2 papers, 2019 to 2020). A neurologic condition associated with the ACQUIRED IMMUNODEFICIENCY SYNDROME and characterized by impaired concentration and memory, slowness of hand movements, ATAXIA, incontinence, apathy, and gait difficulties associated with HIV-1 viral infection of the central nervous system. "Finally, a common CSF marker S100B has been correlated with AIDS dementia complex (ADC) severity and predictive of ADC progression." (PMID 33162998, 2020).
alcohol dependence (2 papers, 2016 to 2023). Physical and psychological dependence on alcohol. "Chronic alcohol dependence can lead to higher S100B protein serum levels, and this is correlated with the amount of alcohol consumption." (PMID 38138951, 2023).
anxiety disorder (2 papers, 2023 to 2025). A category of psychiatric disorders which are characterized by anxious feelings or fear often accompanied by physical symptoms associated with anxiety. "NSE, S100B, tau, and UCH-L1 were raised in participants with probable anxiety disorder on the GAD-7 (eTable 12)." (PMID 39652812, 2025).
Ataxia (2 papers, 2020 to 2025). Ataxia refers to impaired coordination of voluntary muscle movement. "Elevated serum or CSF levels of interleukin-6 (IL-6) and S100B, a marker of astroglial activation and blood-brain barrier (BBB) disruption, were observed in several cases of post-COVID myoclonus and ataxia." (PMID 41404264, 2025).
bladder cancer (2 papers, 2020 to 2022). "Therefore, we analyzed the anesthesia effect of propofol, its impact on serum NGF, S100B protein levels, and immune functions in patients who received bladder cancer surgery." (PMID 36072772, 2022).
brain inflammation (2 papers, 2018 to 2023). "At higher micromolar concentrations, extracellular S100B behaves as DAMP with neurotoxic effects mediated by RAGE and is involved in many neurodegenerative and inflammatory brain diseases." (PMID 30011792, 2018).
cardiac hypertrophy (2 papers, 2010 to 2021). "Chen (2018) showed that S100B genes are the targets of miR-330-3p, and lncRNA X-inactive specific transcript (XIST) promotes S100B expression by harboring complementary binding sites with miR-330-3p, eventually preventing cardiac hypertrophy." (PMID 33982673, 2021).
cholesteatoma (2 papers, 2014 to 2018). A pathologic process characterized by the proliferation of keratinizing squamous epithelium resulting in the accumulation of keratin and cells in the middle ear and/or mastoid. "A significantly higher amount of S100B-positive cells was observed in cholesteatoma tissue in comparison to healthy auditory canal skin." (PMID 29670222, 2018). "A study that compared the expression of S100A1, 2, 3, 4, 5, 6, and S100B in different epithelial lesions in the head and neck found these proteins to be most frequently expressed in craniopharyngeomas and cholesteatomas." (PMID 25093596, 2014). "In addition, co-localization of S100B and Nestin was observable in cells residing within cholesteatoma tissue and auditory canal skin." (PMID 29670222, 2018).
diabetic ketoacidosis (2 papers, 2015 to 2019). The metabolic condition resulted from uncontrolled diabetes mellitus, in which the shift of acid-base status of the body toward the acid side because of loss of base or retention of acids other than carbonic acid is accompanied by the accumulation of ketone bodies in body tissues and fluids. "The aim was to investigate the relationship between NSE and S100B serum concentrations and the severity of diabetic ketoacidosis (DKA) in diabetic children." (PMID 31067852, 2019). "The study aimed to evaluate the pre-treatment and post-treatment oxidant capacity, antioxidant capacity and S100B protein levels in cases of diabetic ketoacidosis (DKA)." (PMID 26316432, 2015).
Fulminant hepatitis (2 papers, 2022 to 2023). Acute hepatitis complicated by acute liver failure with hepatic encephalopathy occurring less than 8 weeks after the onset of jaundice. "Early studies revealed that serum S100b levels in fulminant hepatitis patients and ACLF patients are higher than those in cirrhosis patients and normal controls and unrelated to survival time." (PMID 35911735, 2022). "Later, some scholars found that serum S100b is a useful marker of HE in fulminant hepatitis patients." (PMID 35911735, 2022).
gastric cancer (2 papers, 2019 to 2021). A primary or metastatic malignant neoplasm involving the stomach. "CacyBP/SIP is a target protein of S100B and an inhibitor of gastric cancer." (PMID 34539740, 2021).
HELLP syndrome (2 papers, 2025 to 2026). A life-threatening condition that can potentially complicate pregnancy. "Thus, statistical significance may be weakened, particularly when analyzing the association between S100B levels and different degrees of PE severity or specific clinical manifestations, such as HELLP syndrome or neurological symptoms and signs." (PMID 40563479, 2025). "Additionally, higher S100B levels appear to be correlated with the severity of PE, including neural disturbances and the risk of HELLP syndrome, while postpartum levels may serve as a useful biomarker for the long-term monitoring of CNS injury associated with PE." (PMID 40563479, 2025).
Huntington disease (2 papers, 2020 to 2021). Huntington disease (HD) is a rare neurodegenerative disorder of the central nervous system characterized by unwanted choreatic movements, behavioral and psychiatric disturbances and dementia. "Besides, several proteins including calbindin D, amyloid precursor protein (APP), S100B, and synuclein-alpha (α-synuclein) have been ascertained in neurodegenerative diseases such as AD, Huntington’s disease (HD), multiple sclerosis, and MSA." (PMID 33958996, 2021).
Hypoglycemia (2 papers, 2023). A decreased concentration of glucose in the blood. "In multivariable analyses adjusted for baseline risk factors including NSE and S100B, hypoglycemia remained independently associated with worse scores on working memory (P = 0.006), planning and organization (P = 0.006), and metacognition (P = 0.016)." (PMID 37365667, 2023). "Our results showed that significant changes in S100B, NSE, GFAP, UCHL-1, ACT concentrations, and CK-BB enzyme activity occurred in calves with diarrhea related to hypoglycemia, and hypoglycemia was associated with high mortality." (PMID 38026658, 2023). "While serum S100B concentrations do not change in diabetic patients with metabolically impaired BBB, elevated S100B and NSE concentrations after severe hypoglycemia have been evaluated as indicators of permanent neurological damage." (PMID 38026658, 2023). "Baseline NSE concentrations were significantly higher in patients with than in patients without hypoglycemia (P = 0.001), and baseline S100B concentrations tended to be higher (P = 0.078)." (PMID 37365667, 2023). "In a nested case–control study, our group has shown previously that children with hypoglycemia already had higher NSE and S100B concentrations upon PICU admission, levels that did not increase after a hypoglycemic event." (PMID 37365667, 2023). "None of S100B, NSE, GFAP, UCHL-1, ACT, AM, and CK-BB were found to be significant (p > 0.05) in predicting mortality in calves with hypoglycemia." (PMID 38026658, 2023).